IQCC (IQ motif containing C)
Synonyms: FLJ10547
Tractability: PROTAC: ubiquitination databases record sites on it.
Gene: Protein-coding gene on chromosome 1 (32,205,648 to 32,208,688, forward strand). Ensembl gene ENSG00000160051.
Subcellular location (Human Protein Atlas): Vesicles
Gene Ontology:
Molecular function: protein binding
Genetic constraint (gnomAD): Loss-of-function variants: 26 observed, 31.54 expected, observed/expected ratio (o/e) 0.82, 90% interval 0.6 to 1.14. The upper end of that interval is the gene's LOEUF score, 1.14, which puts it in group 5 of 6, group 1 being the genes least tolerant of losing a copy. Missense variants: 552 observed, 595.94 expected, observed/expected ratio (o/e) 0.93, 90% interval 0.86 to 0.99. Synonymous variants: 220 observed, 229.38 expected, observed/expected ratio (o/e) 0.96, 90% interval 0.86 to 1.07.
Homologues: Orthologues: chimpanzee IQCC (98% identical), macaque IQCC (90% identical), pig IQCC (65% identical), rabbit IQCC (61% identical), dog IQCC (55% identical), mouse Iqcc (50% identical), rat Iqcc (42% identical), zebrafish iqcc (11% identical).